DSC3 (desmocollin 3)
Diseases named in the same sentence as DSC3 in open-access papers (continued):
Sharing a sentence is not in itself a finding about the gene and the disease.
lung carcinoma (7 papers, 2011 to 2025). "Desmocollin 3 (DSC3) was found to be frequently down-regulated in several cancers such as breast, oral, colorectal and lung cancer, and inactivation of DSC3 in these cancers was caused by promoter hypermethylation." (PMID 24664224, 2014). "The expression of SOX30, DSP, JUP and DSC3 were detected in lung cancer cell lines, lung tissues of mice and patients’ tissues by qPCR, WB, Immunofluorescence and Immunohistochemistry." (PMID 29855376, 2018). "To further determine the correction between SOX30 and these genes, we tested for expression of SOX30, DSP, JUP and DSC3 in human lung cancer tissues and adjacent tissues." (PMID 29855376, 2018). "Previous studies have reported that DSC3 acts as a tumor suppressor through inhibiting ERK signaling in human lung cancer." (PMID 29855376, 2018). "Recently, DSC2and DSC3 were found increased in human lung cancer, especially in lung squamous cellcarcinoma.DSC3 was considered as a marker for squamous carcinoma due to its high levels inalmost all lung squamous carcinoma." (PMID 21437242, 2011). "Finally, DSC3 also had multiple recurrent elements and it was up-regulated in the mutant samples from lung cancer (P-value = 0.01)." (PMID 34282050, 2021). "DSC3 acts as a tumor suppressor through inhibiting the EGFR/ERK pathway in lung cancer." (PMID 29855376, 2018). "A functional study conducted thus far has identified DSC3 as a potential tumor suppressor gene, stable transfection of a DSC3 expression vector in lung cancer cell lines showed that ectopic expression of DSC3 inhibited cell proliferation, anchorage-independent growth, migration, as well as invasion." (PMID 24664224, 2014). "In another study, activation of EGFR led to decreased protein levels of DSC3, whereas EGFR inhibition resulted in enhanced expression of DSC3, indicating an EGFR-dependent regulation of DSC3 in lung cancer." (PMID 34527572, 2021). "Among these 8 desmosomal genes, the most obvious change in expression is three tumor suppressor genes for lung cancer, DSP, JUP and DSC3." (PMID 29855376, 2018).
breast tumor (6 papers, 2005 to 2024). "We extended these studies and show that downregulation of DSC3 is a common event in both primary breast tumors as well as breast tumor cell lines, in which we saw a 72% and 79% loss of expression, respectively." (PMID 16168112, 2005). "The purpose of this study was to determine the frequency of DSC3 gene silencing in primary breast tumor specimens and to determine if the loss of expression was due to the aberrant methylation of the DSC3 CpG island promoter." (PMID 16168112, 2005). "In the breast tumor cell lines tested, 11 of 14 (79%) showed a loss of DSC3 expression, whereas HS578T, MDA-MB-468, and UACC3199 showed moderate expression levels." (PMID 16168112, 2005). "Our results indicate that the loss of DSC3 is a common event in breast tumor cell lines at both the mRNA and protein levels and that the loss of expression is frequently correlated with cytosine methylation of its promoter region and an inaccessible chromatin structure." (PMID 16168112, 2005). "Among others, SERPINB5, DSC3, and GABRP have also been linked with malignant neoplasms of the breast." (PMID 39580456, 2024). "We used bisulfite genomic sequencing to analyze the methylation state of the DSC3 promoter region from 32 primary breast tumor specimens." (PMID 16168112, 2005). "In this study, we examined the prevalence of epigenetic silencing of DSC3 gene expression in primary breast tumor specimens." (PMID 16168112, 2005). "They showed that DSC3 was expressed in normal breast while its expression was down-regulated in both primary breast tumors and breast tumor cell lines." (PMID 16168112, 2005). "We also used a quantitative real-time RT-PCR approach, and analyzed all breast tumor specimens for DSC3 expression." (PMID 16168112, 2005). "While functional studies have identified DSC3 as a potential tumor suppressor gene, future studies are necessary to determine the role of DSC3 in breast tumor initiation and progression." (PMID 16168112, 2005). "To further characterize in vitro models for studying the epigenetic state of the DSC3 promoter we extended prior studies and analyzed 14 human breast tumor cell lines for DSC3 expression by quantitative real time RT-PCR." (PMID 16168112, 2005). "Concurrently, we analyzed a panel of breast tumor cell lines for DSC3 expression and concomitant cytosine methylation of its promoter region." (PMID 16168112, 2005). "In this study, we extend our in vitro analysis of DSC3 to the investigation of the frequency of epigenetic silencing of DSC3 expression in primary breast tumor specimens." (PMID 16168112, 2005). "Additionally, DSC3 has been suggested to act as a tumor suppressor, and its silencing is a common event in breast tumors." (PMID 30922380, 2019). "Furthermore, DSC3 expression is limited to cells of epithelial origin and its expression of mRNA and protein is lost in a high proportion of breast tumor cell lines (79%)." (PMID 16168112, 2005). "Therefore, the lack of DSC3 mRNA expression results in a significant loss of DSC3 protein expression in breast tumor cell lines." (PMID 16168112, 2005). "Thus, the greatly reduced expression of DSC3 is a common event in primary breast tumor specimens." (PMID 16168112, 2005). "Therefore, the lack of DSC3 expression in these breast tumor specimens is due in part to both epigenetic and genetic mechanisms of gene silencing." (PMID 16168112, 2005).
prostate carcinoma (5 papers, 2014 to 2025). A carcinoma that arises from epithelial cells of the prostate gland. "Taken together, our data suggests that DNA methylation contributes to down-regulation of DSC3 in prostate cancer, and loss of DSC3 predicts poor clinical outcome." (PMID 24664224, 2014). "Future studies are necessary to expand these observations and investigate specifically the diagnostic/therapeutic potential of DSC3 in prostate cancer." (PMID 24664224, 2014). "Desmocollin 3 (DSC3), a member of the cadherin gene superfamily, is associated with pathogenesis of some cancers, but its role in prostate cancer (PCa) remains largely unknown." (PMID 24664224, 2014). "This suggests that DSC3 transcript loss in prostate cancer can predict poor clinical outcome." (PMID 24664224, 2014). "Dsc3 was markedly lower in MLL- vs. AT1-tumors and reduced expression of this gene has been associated with poor prognosis in prostate cancer patients." (PMID 28472073, 2017). "In this study, we analyzed the expression and methylation patterns of DSC3 in prostate cancer, and more importantly explored the functional role of DSC3 and its potential clinical prediction value." (PMID 24664224, 2014). "We also demonstrated that DSC3 gene is epigenetically silenced in prostate cancer, as treatment of LNCaP cells with the de-methylating agent 5-Aza, induced DSC3 transcript expression." (PMID 24664224, 2014). "To explore the expression of DSC3 transcript in prostate cancer and benign tissues, we used the Oncomine tool to analyze several published microarray gene expression studies." (PMID 24664224, 2014). "Four independent PCa datasets revealed that DSC3 was significantly reduced in prostate cancer tissues compared with benign samples." (PMID 24664224, 2014). "DSC3 expression was significantly and strongly decreased in prostate cancer compared to benign tissues." (PMID 24664224, 2014). "Taken together these observations suggest that DSC3 gene promoter is subject to frequent methylation in both prostate cancer tissues and cell lines." (PMID 24664224, 2014). "To clarify the expression of DSC3 in prostate cancer tissue cohort from a Chinese population, we performed Q-PCR on prostate tissues." (PMID 24664224, 2014). "Next, we explored various publically available dataset for the methylation status of DSC3 gene promoter in prostate cancer." (PMID 24664224, 2014). "Our analysis revealed a strong reduction in DSC3 mRNA expression in prostate cancer tissues as compared to benign specimens." (PMID 24664224, 2014). "To explore the expression of DSC3 in prostate cancer tissues, we performed Q-PCR on a panel of prostate tissues including benign prostate (n = 18), prostate cancer (n = 34)." (PMID 24664224, 2014). "This is the first study, to report a detailed analysis of DSC3 mRNA expression and gene promoter methylation in prostate cancer." (PMID 24664224, 2014). "Our present study thus demonstrates that DSC3 expression is frequently lost in prostate cancer due to promoter hypermethylation similar to previous reports in other solid tumors." (PMID 24664224, 2014). "Towards this we first compared DSC3 expression in prostate cancer from published microarray gene expression studies using the Oncomine tool." (PMID 24664224, 2014). "Our experiments in cell line model also lent support to the notion that DSC3 gene transcription is regulated by CpG island hypermethylation in prostate cancer." (PMID 24664224, 2014). "In order to test whether DSC3 is epigenetically silenced by methylation in prostate cancer, we treated LNCaP cells with a DNA methylation inhibitor, 5-Aza-deoxycytidine (5-Aza)." (PMID 24664224, 2014). "Analysis of the expression of DSC3 might be useful to predict clinical outcomes in prostate cancer patients." (PMID 24664224, 2014). "Collectively, these data suggests DSC3, a member of cadherin superfamily might be playing an important role in prostate cancer progression leading to poor clinical outcome." (PMID 24664224, 2014).
prostate carcinoma (continued). "In summary, DSC3 is down regulated in prostate cancer by DNA hypermethylation." (PMID 24664224, 2014). "Importantly DSC3 expression in prostate cancer clinical specimens was able to predict poor clinical outcome when analyzed for biochemical recurrence." (PMID 24664224, 2014). "Thus, more studies on large prostate cancer tissue cohorts as well as body fluids are needed to further evaluate DSC3 as a methylation biomarker." (PMID 24664224, 2014). "However, little is known about the role of DSC3 in prostate cancer." (PMID 24664224, 2014). "However, little is known about the expression and regulatory mechanisms of DSC3 in prostate cancer." (PMID 24664224, 2014). "However, more studies are required to explore the mechanisms regulating DSC3 in prostate cancer." (PMID 24664224, 2014). "The genes ITGBL1, DSC3, COL4A6, ANGPT1, ARMCX1, MICAL2, and EPHA5 have been recognized as pivotal genes that substantially affect the microenvironment of prostate cancer." (PMID 40943497, 2025). "In addition, analysis of an independent prostate cancer DNA methylation dataset generated by Methylplex Next Generation Sequencing (M-NGS) also revealed DSC3 promoter methylation in LNCaP and not in PrEC." (PMID 24664224, 2014).
colon cancer (3 papers, 2011 to 2018). "In lung and colon cancer, elevated levels of cadherin and desmocollin 3 (DSC3), were associated with improved prognosis." (PMID 29348685, 2018). "In our study, first, we analysed the mRNA expression of DSC3 in eight colon cancer cell lines and found that the expression of DSC3 was significantly downregulated in seven out of eight cell lines." (PMID 21364582, 2011). "We performed real-time RT–PCR to analyse the expression of DSC3 in eight colon cancer cell lines together with one normal colon cell line CCD-33Co." (PMID 21364582, 2011). "Compared with CCD-33Co, DSC3 mRNA expression was found downregulated in seven colon cancer cell lines, except Caco-2." (PMID 21364582, 2011). "The methylation status of DSC3 was determined by MSP in eight colon cancer cell lines." (PMID 21364582, 2011). "We thus compared with the same gene expressions (up-regulated transcripts: SLC16A4, DSC3, ALDOB, EPHX4, ARHGAP24; and down-regulated transcripts (MS4A12, TMIGD1, CASP5) in 5 colon cancer lines: HCT 116, Caco2, HT-29, Lovo, and C32." (PMID 25929336, 2015).
lung adenocarcinoma (3 papers, 2018 to 2023). A carcinoma that arises from the lung and is characterized by the presence of malignant glandular epithelial cells. "Among them, low expression of C12orf56, DLX5, DSC3, FEZF1, GSTA1, H2BC9, IGSF11 and high expression of EREG, CEACAM6, SLC34A2 in lung adenocarcinoma were found to predict poor prognosis for patients." (PMID 37035196, 2023).
squamous cell carcinoma (3 papers, 2011 to 2025). A carcinoma arising from squamous epithelial cells. "DSC3 gene expression has been described in Urobasal A, Urobasal B, squamous cell carcinoma, and Ba/Sq types of bladder cancer previously." (PMID 40422563, 2025). "DSC3 was identified as a highly specific marker for squamous cell carcinoma." (PMID 38652547, 2024).
colorectal tumors (2 papers, 2011 to 2015). "The specificity of MSP in CRC cell lines encouraged us to analyse the methylation status of DSC3 DNA in 99 primary colorectal tumours by using the same primer pairs." (PMID 21364582, 2011). "Thus, up-regulated expression was greater in PMP for SLC16A4, DSC3, ALDOB compared with colorectal tumors." (PMID 25929336, 2015).
lung squamous cell carcinoma (2 papers, 2014 to 2017). "In primary lung tumors, DSC3 was a potential diagnostic marker for lung squamous cell carcinoma." (PMID 24743794, 2014). "Desmocollin-3 was the most specific marker for poorly differentiated squamous cell lung carcinoma (100%), followed by CK5/6 (98.3%), glypican-3 (94.8%), Sox2 (94.8%), S100A2 (81%), S100A7 (75.9%), thrombomodulin (72.4%), p63 (48.3%), and HMCK (36.8%)." (PMID 28510121, 2017). "When analyzing only poorly differentiated tumors, HMCK was the most sensitive marker for squamous cell lung carcinoma (100%), followed by p63 (97.8%), CK5/6 (87.0%), Sox2 (71.7%), thrombomodulin (58.7%), desmocollin-3 (52.2%), S100A2 (50%), glypican-3 (45.7%), and S100A7 (45.7%)." (PMID 28510121, 2017).
lymph node metastasis (2 papers, 2017 to 2023). "DSC3 (Desmocollin 3), a member of the cadherin superfamily, has been associated with lymph node metastasis in oral squamous cell carcinoma." (PMID 28225791, 2017). "The abnormal expression of DSC3, DSG3, and β-catenin was found in oral carcinomas and that the reduced or absent expression of β-catenin had a positive correlation with reduced or absent expression of DSC3 in 24 patients with lymph node metastasis." (PMID 36982827, 2023).
neuroblastoma (2 papers, 2014 to 2015). Neuroblastoma (NB) is the most common solid, extracranial childhood tumor. "Furthermore, two intergenic mutations between the cadherin genes CDH2 and desmocollin 3 (DSC3) disrupt a non-coding regulatory element and alter gene expression in a human neuroblastoma cell line." (PMID 24995881, 2014).
non-small cell lung carcinoma (2 papers, 2023 to 2024). A group of at least three distinct histological types of lung cancer, including non-small cell squamous cell carcinoma, adenocarcinoma, and large cell carcinoma. "In addition, desmocollin 3 is an essential protein for cell adhesion and desmosome formation and may enhance angiogenesis with metastasis in nasopharyngeal carcinoma and is considered a biomarker for some cancers, such as non-small cell lung cancer." (PMID 37753171, 2023). "In fact, because DSC3 is identified as a predictive biomarker for Mw efficacy as a cancer treatment, Mw has been granted orphan drug status by the FDA for the treatment of DSC3-expressing non-small cell lung cancers." (PMID 39534596, 2024).
pemphigus vulgaris (2 papers, 2010 to 2014). Pemphigus is a group of chronic autoimmune skin diseases characterized by blister formations on the outer layer of the skin and the mucous membranes. "Furthermore, PKP3 binds in vivo to several other primary pemphigus vulgaris autoantigens including DSG3, DSG1, DSC1, and DSC3." (PMID 24988487, 2014).
sarcoma (2 papers, 2011 to 2024). A usually aggressive malignant neoplasm of the soft tissue or bone. "The acquisition of the epithelial markers E-cadherin and desmocollin 3 in four of the five chondrosarcoma cell lines is consistent with reports showing that sarcomas can to some degree transition through MET from their parental cell lineage." (PMID 21559267, 2011).
skin cancer (2 papers, 2012 to 2018). "In addition, it is notable that in another model, combined oncogenic K-Ras expression and Dsc3 deletion in mouse skin accelerated skin cancer development relative to Dsc3-expressing controls, suggesting a tumor suppressor role for Dsc3." (PMID 23185521, 2012).
alopecia (1 paper, 2019). Hair loss usually from the scalp. "DSC3/DSG3 mice show more lesions and alopecia on the face and in the periocular area, erosions on the forelegs, with exacerbated erythema, while in DSC3 mice intense erythema and patchy hair loss are the main phenotypic aspects." (PMID 31275323, 2019).
bladder cancer (1 paper, 2025). "We also evaluated the relationship of DSC3 expression with tumor immune infiltrate and bladder cancer subtypes." (PMID 40422563, 2025). "The DSC3 gene was first cloned from bladder cancer and was found to be higher in bladder cancer tissues compared to normal bladder tissue." (PMID 40422563, 2025). "To further elucidate the correlation between DSC3 and markers of bladder cancer molecular subtypes, we divided samples across molecular subtypes into DSC3 high (upper quartile (UQ)) and DSC3 low (lower quartile (LQ)) groups." (PMID 40422563, 2025). "Bladder cancer samples that expressed DSC3 were more likely to have intratumoral TIL than stromal TIL." (PMID 40422563, 2025). "Because DSC3 expression has been previously identified in the basal/squamous (Ba/Sq) type of bladder cancer, we evaluated DSC3 expression level in basal squamous, neuronal, and luminal molecular subtypes of bladder cancer as defined in the TCGA dataset." (PMID 40422563, 2025). "We evaluated DSC3 protein expression in bladder cancer and its relationship with the stage of disease as well as with tumor immune infiltrate (TII) to identify the potential of using CADI-05 in the treatment of bladder cancer." (PMID 40422563, 2025). "In this study, a positive correlation with TCIG and a negative correlation with TPIG on DSC3 enrichment suggests immune mechanisms may not play a significant role in DSC3-expressing bladder cancer." (PMID 40422563, 2025).
carpal tunnel syndrome (1 paper, 2020). Entrapment of the median nerve in the wrist that is characterized by numbness, tingling and painful movement. "We speculate that cg16492377 methylation association with carpal tunnel syndrome may be related to changes in DSC3 transcriptomic regulation." (PMID 33203445, 2020). "Nominally significant differences were observed for CpG sites mapped in other surrounding loci: DSC2 (cg02936398, Carriers vs. Controls); DSG2 (cg14311811, hATTR patients vs. asymptomatic carriers); DSC3 (cg16492377, carpal tunnel syndrome in hATTR patients)." (PMID 33203445, 2020).
cholesteatoma (1 paper, 2015). A pathologic process characterized by the proliferation of keratinizing squamous epithelium resulting in the accumulation of keratin and cells in the middle ear and/or mastoid. "Desmocollin-3 (DSC3) likely contributes to this friability, as loss of function is found in skin fragility disorders, which matches the abundance profile we observed with decreased levels (3.42-fold) in cholesteatoma compared to skin, but above that seen in mucosa." (PMID 26608071, 2015).